ERCC2 (ERCC excision repair 2, TFIIH core complex helicase subunit)
Diseases named in the same sentence as ERCC2 in open-access papers (continued):
Sharing a sentence is not in itself a finding about the gene and the disease.
head and neck cancer (7 papers, 2012 to 2025). A primary or metastatic malignant neoplasm affecting the head and neck. "Harth et al33 analysed polymorphisms of genes in head and neck cancer and in a subgroup of non‐smokers, variants of the ERCC2 gene were predominant but when stratifying for smokers, CYP1B1 variant produced main effect." (PMID 30133114, 2018). "Additionally, ERCC2 Lys751Gln and Asp312Asn polymorphisms are prognostic factors for locally advanced head and neck cancer after definitive cisplatin chemoradiotherapy." (PMID 40777111, 2025). "They found that the expression of ERCC2 was associated with the expression of Ki-67 and an aggressive cancer phenotype and concluded that ERCC2 might be used as a biomarker for improved diagnostic and prognostic value in head and neck cancer." (PMID 30417012, 2018). "The ERCC2 gene Lys751Gln and Asp312Asn SNP have been shown to correlate with a diminished response to cisplatin-based chemotherapy or radiotherapy in patients with head and neck cancer." (PMID 40777111, 2025).
pancreatic cancer (7 papers, 2011 to 2023). "The current study is the first meta-analysis of the association between ERCC2 rs13181 and the risk of pancreatic cancer." (PMID 28223548, 2017). "Many previous genetic association studies on pancreatic cancer risk have focused on the effects of single nucleotide polymorphisms in ERCC2 gene." (PMID 28223548, 2017). "This is, to our knowledge, the first comprehensive meta-analysis concerning the association between ERCC2 rs13181 and the risk of pancreatic cancer." (PMID 28223548, 2017). "Single nucleotide polymorphisms (SNPs) of Excision repair cross-complementing group 2 (ERCC2) gene are suspected to affect the risk of pancreatic cancer." (PMID 28223548, 2017). "Recently, more studies have shown that the ERCC2 gene polymorphisms plays a key role in the tumorigenesis of pancreatic cancer." (PMID 28223548, 2017). "Many studies have reported the association between ERCC2 Lys751Gln polymorphism (rs13181) and the susceptibility to pancreatic cancer, but the outcomes remained controversial." (PMID 28223548, 2017). "In conclusion, our meta-analysis suggests that ERCC2 Lys751Gln polymorphism is a risk factor of pancreatic cancer for all of the ethnicities, and presence of this polymorphism in Asian population will increase their susceptibility to pancreatic cancer." (PMID 28223548, 2017). "Our results indicate that the ERCC2 Lys751Gln polymorphism might be important in stimulating the development of pancreatic cancer, especially for Asians." (PMID 28223548, 2017).
anemia (5 papers, 2017 to 2024). A reduction in the number of red blood cells, the amount of hemoglobin, and/or the volume of packed red blood cells. "Regarding infectious complications, the model selected 6 SNPs: rs1799793 in ERCC2 gene, Level 3, described in the literature to be associated with toxicity of platinum-compounds and etoposide, producing anemia and pneumonitis." (PMID 32295184, 2020). "rs1799793 (χ2 test P = 2.71 × 10−5; OR = 7.91, 95%CI:2.02–30.96, P = 0.003) in ERCC2 was significantly associated with anemia." (PMID 28924235, 2017). "Patients with ERCC2 rs1799793 A/A were at risk of developing severe anemia." (PMID 30914949, 2019). "Patients with ERCC2 rs1799793 A/A genotype were at higher risk of developing anemia." (PMID 30914949, 2019). "Univariate analyses for toxicity showed statistically significant associations between ERCC2 rs50872 (p = 0.03 in a recessive model) and XRCC1 rs25487 (p = 0.04 in a recessive model) and anemia." (PMID 39339159, 2024). "Polymorphisms in GTF2H1, ERCC2 and RPA1 showed significant association with anemia." (PMID 28924235, 2017).
cataract (5 papers, 2011 to 2022). Partial or complete opacity of the crystalline lens of one or both eyes that decreases visual acuity and eventually results in blindness. "Our finding that ERCC2 is expressed in the lens and that the S737P mutation leads to a recessive form of cataracts makes it very likely that the association of ERCC2 SNPs with cataracts holds true also in human populations." (PMID 25951169, 2015). "Using our new model of the RCO015 (Ercc2S737P) mutant mice, we focused on the eye phenotype to find out how Ercc2 is involved in the formation of cataracts." (PMID 25951169, 2015). "Here we report for the first time a mouse Ercc2 mutant suffering from recessive cataracts." (PMID 25951169, 2015).
colon cancer (5 papers, 2013 to 2025). "ERCC2 expression was associated with worse overall survival (OS) in colon cancer (HR = 1.53, P = 0.043)." (PMID 29568775, 2018). "Multivariate analysis indicated that high ERCC2 expression was associated with worse overall survival (OS) of colon cancer (adjusted HR = 1.53, 95% CI = 1.01–2.31, P = 0.043)." (PMID 29568775, 2018). "ERCC2 expression was associated with worse OS of colon cancer and subgroup analysis suggested a more significant result in males with a HR value of 1.84." (PMID 29568775, 2018). "The current investigation with JQ1 + 6-SFN defined ERCC2 as a key mechanistic target in human colon cancer cells, with the potential to impact overall survival in CRC patients." (PMID 33809839, 2021). "Constitutive ERCC2 mRNA expression was high in colon cancer cells (SW480, HCT116) compared to normal colon epithelial cells (CCD841), as assessed by RT-qPCR (p < 0.001)." (PMID 33809839, 2021). "Per this background and based only on the observed changes of ERCC2 and XRCC1 mRNA expression, we may hypothesize that miR-92a-3p improves platinum sensitivity in colon cancer cell lines by downregulation of ERCC2 and XRCC1 expression." (PMID 38659583, 2024). "Second, ERCC2 was the most highly downregulated RNA transcript in human colon cancer cells, plus Ercc2 in rat tumors, after treatment with the histone deacetylase 3 (HDAC3) inhibitor sulforaphane (SFN) plus JQ1, which is an inhibitor of the bromodomain and extraterminal domain (BET) family." (PMID 33809839, 2021). "Because CtIP and CCAR2 were previously identified as mechanistic targets for SFN and SFN + JQ1, respectively, we used CRISPR/Cas9 in HCT116 colon cancer cells and observed markedly higher basal ERCC2 expression in CtIP–/– and CCAR2–/– cell lines compared to the parental cell line." (PMID 33809839, 2021). "Second-generation BET degrader plus HDAC3-specific inhibition (dBET6 + BG45) was highly effective in metastasis-lineage colon cancer cells, exhibiting marked downregulation of ERCC2 in monolayers, spheroids, and xenografts, coinciding with antitumor outcomes in vivo." (PMID 33809839, 2021). "Thus, mechanisms that also effectively downregulate ERCC2 might provide a ‘tipping point’ in colon cancer cells, being unable to mount an effective DNA damage response, and triggering apoptotic or alternative cell-death pathways." (PMID 33809839, 2021). "The present study showed an inverse correlation between miR-92a-3p and ERCC2 and XRCC1 mRNA expression in SW620 colon cancer cells, which itself proposes a gap in knowledge about the mechanisms of acquired chemoresistance to long-term FOLFOX chemotherapy." (PMID 38659583, 2024). "Through a different mechanism, long-term chemotherapy may induce chemoresistance by upregulation of miR-92a-3p, and subsequent downregulation of ERCC2 and XRCC1 expression in colon cancer, promoting hypermutability and tumor heterogeneity." (PMID 38659583, 2024). "To assess whether endogenous ERCC2 protein expression levels might account for the metastatic cell line SW620 being more sensitive to PROTACs than the SW480 parental counterpart, we immunoblotted for ERCC2 in a panel of colon cancer and normal colonic epithelial cell lines." (PMID 33809839, 2021).
esophageal squamous cell carcinoma (5 papers, 2013 to 2021). Esophageal squamous cell carcinoma (ESCC) is a type of esophageal carcinoma (EC) that can affect any part of the esophagus, but is usually located in the upper or middle third. "In a large case-control study of 1126 esophageal squamous cell carcinomas (ESCC) patients and 1131 controls, we genotyped two SNPs in ERCC2 (rs238406 G > T and rs13181 T > G) and assessed their associations with ESCC risk." (PMID 25209371, 2014). "These three ERCC2 SNPs are found to be associated with a reduced repair of aromatic DNA adducts and an increasing risk of lung cancer, bladder cancer, esophageal squamous cell carcinoma (ESCC) and head and neck cancer." (PMID 23593158, 2013).
nasopharyngeal carcinoma (5 papers, 2015 to 2023). A carcinoma arising from the nasopharyngeal epithelium. "The second gene, ERCC2, encoding an adenosine triphosphate (ATP)-dependent DNA helicase, is frequently mutated in families with increased nasopharyngeal carcinoma risk." (PMID 37762649, 2023).
sarcoma (5 papers, 2013 to 2025). A usually aggressive malignant neoplasm of the soft tissue or bone. "In a large study determining sarcoma risk, rare variant burden analysis identified germline ERCC2 variants in 23 patients with various sarcoma types, suggesting that ERCC2 may be a newly recognized sarcoma susceptibility gene." (PMID 40563612, 2025). "In addition, the genotyping of the SNPs rs17655 (Lys751Gln) in ERCC5 and rs13181 (Asp1104His) in ERCC2 revealed the potential implication of the Asp1104His polymorphism in the occurrence of chromosomal translocations associated with specific sarcoma subtypes." (PMID 35955506, 2022). "Neither RAD23B nor ERCC2 have been linked to any type of sarcoma." (PMID 23637977, 2013).
bladder tumors (4 papers, 2011 to 2025). "The nucleotide excision repair (NER) helicase ERCC2 carries heterozygous missense mutations in approximately 10% of bladder tumors, and these may predict sensitivity to cisplatin treatment." (PMID 40829180, 2025). "According to the COSMIC catalog, SBS5 was found to be increased in bladder tumors with mutations in the DNA excision repair gene ERCC2, whereas signature SBS30 was found to be related to a deficiency in base excision repair due to inactivating mutations in NTHL1." (PMID 37906280, 2023). "Finally, we have reported that the SNP in the XPC, ERCC2 and ERCC5 genes don't affect the bladder tumors phenotype." (PMID 21426550, 2011). "However, this genetic context differs from most bladder tumors, in which the heterozygous missense ERCC2 mutations are present without loss of heterozygosity (LOH) of WT ERCC2 allele(s)." (PMID 40829180, 2025).
cerebrooculofacioskeletal syndrome (4 papers, 2016 to 2021). "The ERCC2 DNA repair factor is associated with complex phenotypes such as cerebrooculofacioskeletal syndrome 2 (MIM 610756), trichothiodystrophy 1 (MIM 601615), xeroderma pigmentosum D (MIM 278730)." (PMID 33095795, 2020). "At the moment, four different genes are known to cause COFS syndrome: ERCC6 (COFS1, MIM #214150), ERCC2 (COFS2, MIM #610756), ERCC5 (COFS3, MIM #616570), and ERCC1 (COFS4, MIM #610758)." (PMID 33766032, 2021).
cervical carcinoma (4 papers, 2019 to 2025). A carcinoma arising from either the exocervical squamous epithelium or the endocervical glandular epithelium. "However, the ERCC2 Asp312Asn polymorphism may reduce the susceptibility to cervical cancer in Asian women." (PMID 40777111, 2025). "In addition, the recessive gene model of ERCC2 Asp312Asn may reduce the susceptibility to cervical cancer in the Asian population." (PMID 40777111, 2025). "In contrast, the ERCC2 Asp312Asn polymorphism did not elevate the risk of gynecologic neoplasms, and the recessive gene variant was even protective against cervical cancer (AA vs GA+GG : OR 0.53, 95%CI 0.34-0.83, P=0.005)." (PMID 40777111, 2025). "A recent study analyzed the expression of XRCC1, ERCC2, ERCC4 and ERCC1 in cervical tissue samples and showed that the levels of both mRNA and protein were lower in squamous intraepithelial lesions and cervical cancer samples than in samples from control patients." (PMID 30674977, 2019).
neutropenia (4 papers, 2015 to 2024). A decrease in the number of neutrophils found in the blood. "For ERCC2 rs13181 (Lys751Gln), grade 2-4 neutropenia was more frequent among individual with 751 Lys/Lys genotype in 62 NSCLC patients treated with cisplatin and docetaxel (p = 0.04)." (PMID 39234108, 2024). "Polymorphisms in ERCC2, ERCC6, DDB2, RPA1, POLD1 and POLD3 presented significant association with neutropenia." (PMID 28924235, 2017). "Here, we evaluated additional SNPs on the candidate genes: CYP3A4*22, GSTP1, ERCC2, SLCO1B1, and ABCG2, but did not observe a significant relationship with neutropenia and neurotoxicity except for XRCC3 316A>G rs1799794 for GG+AG alleles (p = 0.03)." (PMID 29163177, 2017).
brain tumor (3 papers, 2014 to 2024). "Most probably, the brain tumor resulted from an increased rate of mutations due to the defective DNA repair caused by the ERCC2 mutation." (PMID 38028607, 2023). "The homozygous ERCC2 mutation (NM_000400, c.2048 G>A, p.R683Q) was present in the patient and his brother with a brain tumor, while it is heterozygous in the unaffected brother." (PMID 38028607, 2023). "We think that the identified homozygous ERCC2 p.R683Q mutation could have contributed to the tumorigenesis in the patient’s brother (36 years old), who has a brain tumor." (PMID 38028607, 2023). "Future studies may address the effect of the ERCC1 rs3212986 and ERCC2 rs13181 polymorphism on different histological brain tumor subtypes to provide a better understanding of tumor pathogenesis." (PMID 25674148, 2014).
glioblastoma (3 papers, 2014 to 2025). The most malignant astrocytic tumor (WHO grade IV). "Unfortunately, only two studies in Caucasian populations provide genetic data of ERCC2 Lys751Gln polymorphism for glioblastoma multiforme and nonglioblastoma multiforme, respectively." (PMID 24763305, 2014).
hereditary cancer (3 papers, 2019 to 2023). Malignant neoplasms occurring in families at a rate greater than that expected by chance and caused by germline mutations in a specific gene. "Germline mutations in ERCC2 have been rarely found associated with hereditary cancer." (PMID 38028607, 2023). "In addition to mutations associated with risk of hereditary cancer, pathogenic/likely pathogenic mutations were detected in ERCC2 (n = 1), FANCA (n = 1), FANCC (n = 1), HNF1A (n = 1), PRF1 (n = 1) RECQL4 (n = 2), WRN (n = 1), and XPA (n = 1)." (PMID 31963545, 2020). "It is also interesting to highlight candidate genes involved in hereditary cancer (BRCA2, BLM, ERCC2, SMARCA4) or connected to inherited CRC, such as Cowden syndrome (SEC23B) and Peutz–Jeghers syndrome (STK11IP)." (PMID 30871259, 2019).
ichthyosis (3 papers, 2018 to 2021). Disorders of cornification that are characterized by visible scaling and/or hyperkeratosis of most or all of the skin. "TTD1 (OMIM 601675) is caused specifically by variants in ERCC2/XPD (OMIM 126340), which encodes a helicase subunit of TFIIH, and typically causes ichthyosis, photosensitivity, hair abnormalities and intellectual and physical disabilities." (PMID 33670118, 2021).
laryngeal carcinoma (3 papers, 2014 to 2019). Carcinoma that arises from the laryngeal epithelium. "Beginning with DNA repair genes, less common genotypes in ERCC1 rs11615 (p = 0.011, OR = 0.288 (CI 95% = 0.110–0.751) in a recessive model) and ERCC2 rs13181 (p = 0.046, OR = 0.375 (0.143–0.982) in a codominant model) were associated with a lower risk of laryngeal cancer." (PMID 30959967, 2019). "Polymorphisms in other NER genes including ERCC1, ERCC2, ERCC3, ERCC4, ERCC5, and XPA have also been reported to pose as an increased risk in Laryngeal Cancer." (PMID 30410671, 2018).
lung adenocarcinoma (3 papers, 2009 to 2023). A carcinoma that arises from the lung and is characterized by the presence of malignant glandular epithelial cells. "Among these SNPs, heterozygous carriers of the ERCC2 751AC genotype had a 1.66-fold risk of lung adenocarcinoma compared with those carrying the homozygous wild genotype (95%CI 1.07-2.59, P = 0.024)." (PMID 20003391, 2009). "As a result, the combined ERCC2 751AC/CC was associated with an increased risk of lung adenocarcinoma with an adjusted OR of 1.64 (95%CI 1.06-2.52, P = 0.025)." (PMID 20003391, 2009). "This study showed that the individuals with the combined ERCC2 751AC/CC genotypes were at an increased risk for lung adenocarcinoma compared with those carrying the AA genotype [adjusted odds ratios (OR) 1.64, 95% confidence interval (CI) 1.06-2.52]." (PMID 20003391, 2009). "It suggests that the polymorphism of ERCC2 codon 751 plays an important role in the development of lung adenocarcinoma in non-smoking females." (PMID 20003391, 2009). "Our results show that non-smoking females carrying ERCC2 751C variant allele were at an increased risk for lung adenocarcinoma compared with those carrying AA genotype (adjusted OR = 1.64)." (PMID 20003391, 2009). "Our results show that the ERCC2 751C allele or the haplotypes encompassing the variant allele are associated with risk of lung adenocarcinoma in Chinese nonsmoking female population." (PMID 20003391, 2009). "Our study indicated that ERCC2 751 polymorphism may indeed be of functional importance for lung adenocarcinoma among non-smoking female population." (PMID 20003391, 2009). "The results of the present study indicate that ERCC2 751 polymorphism (rs13181) might be a genetic risk modifier for lung adenocarcinoma in non-smoking females in China." (PMID 20003391, 2009). "However, the associations have not been found between ERCC2 751 or 312 polymorphism and survival of lung adenocarcinoma." (PMID 20003463, 2009). "ERCC2 751 polymorphism may be a genetic risk modifier for lung adenocarcinoma in non-smoking females in China." (PMID 20003391, 2009). "To test above possibility, we assess the relationship between survival of lung adenocarcinoma patients and SNPs in three DNA repair genes, including excision repair cross-complementing group 1 (ERCC1) and group 2 (ERCC2), and X-ray repair cross-complementing group 1 (XRCC1)." (PMID 20003463, 2009). "This study aimed to investigate the relationship between polymorphisms in ERCC2, ERCC1 and XRCC1 genes and survival of non-smoking female patients with lung adenocarcinoma." (PMID 20003463, 2009). "In summary, our study sheds light on the relationship between polymorphisms in the DNA repair gene ERCC2 and ERCC1 with environmental risk factors and susceptibility to lung adenocarcinoma in nonsmoking females in northeast China." (PMID 20003391, 2009). "The effect of the ERCC2 and ERCC1 polymorphisms, and also of the haplotypes encompassing these two genes, on susceptibility of lung adenocarcinoma in non-smoking females has not been reported so far." (PMID 20003391, 2009). "This study aimed to investigate the association between the ERCC2 751, 312 and ERCC1 118 polymorphisms and the risk of lung adenocarcinoma in Chinese non-smoking females." (PMID 20003391, 2009).
progeria (3 papers, 2010 to 2026). "Among these disorders are Cockayne syndrome which is caused by mutations in ERCC6 (CSB) or ERCC8 (CSA), trichothiodystrophy (TTD) caused by mutations in ERCC2 (XPD), ERCC3 (XPB), or TTDA (GTF2H5) and XPF-ERCC1 progeria (XFE) caused by dysfunction of the XPF-ERCC1 heterodimer." (PMID 23947592, 2013).